UBE2C (ubiquitin conjugating enzyme E2 C)
Diseases named in the same sentence as UBE2C in open-access papers (continued):
Sharing a sentence is not in itself a finding about the gene and the disease.
glioma (25 papers, 2016 to 2024). A benign or malignant brain and spinal cord tumor that arises from glial cells (astrocytes, oligodendrocytes, ependymal cells). "Next, we explored the underlying mechanisms through which UBE2C triggers drug resistance to TMZ in gliomas." (PMID 38634120, 2024). "In this study, we explore the role of UBE2C in regulating temozolomide (TMZ) resistance in glioma and investigate the underlying mechanisms involved." (PMID 38634120, 2024). "In the present study, bothin vivo andin vitro experiments were carried out in this study to explore the role of UBE2C in regulating TMZ resistance in glioma and to elucidate the underlying mechanisms involved." (PMID 38634120, 2024). "In glioma, researchers have reported thatUBE2C is highly expressed and functions as an oncogene; moreover, high expression of UBE2C is associated with poor prognosis in glioma patients." (PMID 38634120, 2024). "It has been shown that the Forkhead box transcription factor M1 (FoxM1) triggers UBE2C transcription by binding to its promoter regions and is associated with poor prognosis in gliomas." (PMID 37958776, 2023). "Next, we investigated the mechanisms underlying UBE2C-mediated TMZ resistance in glioma." (PMID 38634120, 2024). "Consistently, we found that UBE2C was more highly expressed in glioma tissues than in normal brain tissues, and its high expression was linked to a lower overall survival rate in patients with gliomas." (PMID 38634120, 2024). "Moreover, high FoxM1 and UBE2C expression levels in gliomas were closely associated with a poor prognosis." (PMID 28767320, 2017). "However, the specific role of UBE2C in TMZ resistance in glioma and the underlying mechanisms remain unknown." (PMID 38634120, 2024). "Additionally, it has been reported that UBE2C is implicated in drug resistance in gliomas." (PMID 38634120, 2024). "Overexpression of UBE2C rescues glioma cells from TMZ-mediated apoptosis and enhances cell viability." (PMID 38634120, 2024). "For instance, Alafateet al. reported that the upregulation of AURKB and UBE2C led to unfavourable outcomes, such as shorter overall survival and therapy resistance, in glioma patients." (PMID 38634120, 2024). "For example, Maet al. reported that UBE2C expression was elevated in glioma, which predicted a worse prognosis." (PMID 38634120, 2024). "Collectively, thein vivo assay further demonstrated that downregulation of UBE2C sensitized glioma cells to TMZin vivo." (PMID 38634120, 2024). "Then, we explored the role of UBE2C in regulating cell resistance to TMZ usingin vitro experiments in glioma." (PMID 38634120, 2024). "The role of UBE2C in the aggressive progression of various cancers, including tongue squamous cell carcinoma, renal cell carcinoma, thyroid carcinoma, and glioma, has been well‐documented." (PMID 38577722, 2024). "Our results show that both the mRNA and protein levels of UBE2C are significantly elevated in the brain tissues of glioma patients, especially in those of TMZ-resistant patients." (PMID 38634120, 2024). "UBE2C is overexpressed in gliomas, and its overexpression has been reported to be correlated with the drug resistance of gliomas to some extent." (PMID 38634120, 2024). "TMZ-resistant cell lines are constructed to explore the role of UBE2C in regulating glioma cell viability and TMZ resistance." (PMID 38634120, 2024). "The findings revealed that UBE2C was positively associated with cell cycles of AML, CML, BRCA, GBM, glioma, HGG, HNSCC, LUAD, RCC, OV, PC, MEL, and RB." (PMID 38370368, 2024).
glioma (continued). "UBE2C expression was analyzed in astrocytic tumors, and authors concluded that GB exhibits high levels of this protein compared with low-grade astrocytomas, indicating a correlation between UBE2C expression and glioma tumor grade." (PMID 37958776, 2023). "It was also observed that UBE2C knockdown suppresses glioma cell growth by 40% in comparison to control cells and induces autophagy through inactivation of the PI3K/Akt/mTOR pathway." (PMID 37958776, 2023). "In the Sun dataset of glioma (GEO ID: GSE4290), expression of the genes UBE2S and UBE2C, which encode ubiquitin conjugases important for cell-cycle progression, distinguished GBM from AS and ODG." (PMID 35896929, 2023). "Meanwhile silencing of UBE2C in glioma leads to significant inhibition of the PI3K-Akt-mTOR pathway, while avoiding autophagy." (PMID 36291283, 2022). "UBE2C, BIRC5, and CCNB2 were reported to be oncogenic and are associated with several cancers including glioma." (PMID 36105094, 2022). "Several cell cycle regulatory genes are significantly upregulated in canine OG, however, we selected KIF11 and UBE2C, which are commonly upregulated in canine and human glioma, for further evaluation at the protein level." (PMID 31475119, 2019). "Transcription factor FoxM1 positively regulates UBE2C expression to protect glioma cells from autophagic death." (PMID 30914455, 2019). "Corroborating our results, a very recent study reported that FOXM1 binds onto UBE2C promoter and triggers its transcription in glioma cells and, therefore, protects them from autophagic cell death." (PMID 29596365, 2018). "Next, we investigated UBE2C expression in 154 glioma tissues of different grades according to the WHO classification and 27 normal human brain (NHB) tissues." (PMID 28767320, 2017). "Our study focused on determining the molecular mechanism by which FoxM1 represents a pivotal transcriptional regulator of UBE2C, whose deregulation induces autophagic death in glioma cells." (PMID 28767320, 2017). "First, U87-MG, U251, Ln18 and U373 cells were used in our study to examine the expression of UBE2C in glioma cell lines." (PMID 28767320, 2017). ",28 analyzed the UBE2C expression levels in gliomas of different grades and further demonstrated that UBE2C knockdown inhibits glioma cell proliferation and enhances apoptosis." (PMID 28767320, 2017). "In this study, we evaluated the effects of UBE2C on glioma cell autophagy, and we found that si-UBE2C triggered a significant increase in the conversion of LC3B-I to LC3B-II." (PMID 28767320, 2017). "In this study, we found that Forkhead box transcription factor M1 (FoxM1) overexpression increased UBE2C expression, whereas FoxM1 suppression inhibited UBE2C expression in glioma cells." (PMID 28767320, 2017). "Collectively, our findings provide clinical and molecular evidence that FoxM1 promotes glioma progression by enhancing UBE2C transcription and that the inhibition of UBE2C partially induces autophagic glioma cell death." (PMID 28767320, 2017). "Taken together, these findings suggest that FoxM1 transcriptionally regulates UBE2C expression by directly binding to the UBE2C promoter in glioma cells." (PMID 28767320, 2017). "The colocalization of UBE2C and FoxM1 expression was confirmed by a double immunofluorescence assay, showing that the expression levels of both UBE2C and FoxM1 were correlated with the glioma histological grade." (PMID 28767320, 2017). "Previously, a series of in vitro and in vivo studies indicated that FoxM1 and UBE2C displayed high expression and activity levels in many cancer types, including glioma." (PMID 28767320, 2017). "Clinicopathological investigations have proposed an up-regulation of ubiquitin-conjugating enzyme E2C (UBE2C) in gliomas." (PMID 28767320, 2017).
glioma (continued). "In this study, we also found that UBE2C expression was strongly correlated with FoxM1 expression in gliomas." (PMID 28767320, 2017). "In glioma cell lines (i.e., U87-MG, U251, ln18, and U373), UBE2C, a known glioma tumor progression protein, harbors two FOXM1 binding sites on its promoter, strongly suggesting that it could be another direct transcriptional target of FOXM1." (PMID 39594778, 2024). "Compared with those in normal brain tissues, the mRNA and protein levels of UBE2C were elevated approximately 1-fold and 0.8-fold, respectively, in the brain tissues of glioma patients who were sensitive to TMZ but 5-fold and 2.2-fold, respectively, in patients with TMZ resistance." (PMID 38634120, 2024). "Because inhibition of UBE2C promotes autophagic cell death in glioma cells, the FOXM1/UBE2C axis could be essential in developing resistance to therapies, and its targeting holds therapeutic value." (PMID 39594778, 2024). "Alafateet al. reported that UBE2C expression was relevant to the treatment resistance of gliomas, suggesting that UBE2C might play a role in modulating chemotherapy resistance in gliomas." (PMID 38634120, 2024). "The combined upregulation of UBE2C and aurora kinase B (AURKB), an important player in the cell cycle, is associated with a dismal outcome, therapeutic resistance, and reduced overall survival in glioma patients." (PMID 37958776, 2023). "The role of UBE2C has been studied in brain tumors, including gliomas, meningiomas, and BM." (PMID 37958776, 2023). "Aurora kinase B (AURKB) and ubiquitin-conjugating enzyme E2 C (UBE2C) are involved in the tumorigenesis of gliomas and other malignancies, and simultaneously elevated expression of AURKB and UBE2C is strongly correlated with poor prognosis and therapy resistance in glioma." (PMID 32642801, 2020). "In addition, we determined FoxM1 expression in the same series of glioma specimens; a pattern similar to that of UBE2C expression was observed." (PMID 28767320, 2017). "Moreover, to confirm the clinical and pathological relevance of the Western blot, qRT-PCR and IHC results, we performed a clinicopathological analysis of UBE2C in 154 glioma cases." (PMID 28767320, 2017). "Moreover, UBE2C siRNA (si-UBE2C) significantly induced glioma cell autophagy and increased both mCherry-LC3 punctate fluorescence and LC3B-II/LC3-I expression." (PMID 28767320, 2017). "In addition, high FoxM1/UBE2C expression was significantly correlated with poor prognosis in glioma." (PMID 28767320, 2017). "Moreover, our findings indicated another type of programmed cell death aside from apoptosis and elaborated upon the process of autophagy induced by si-UBE2C in glioma cells." (PMID 28767320, 2017). "Our findings indicate a novel role of FoxM1 in the development of glioma and initially present an autophagy-related function of UBE2C, which may be a feasible target for molecular glioma therapies." (PMID 28767320, 2017).
glioma (continued). "In addition to its role in chemotherapy and radiotherapy resistance, FOXM1 is involved in reducing autophagic death in glioma cells by regulating the expression of Ubiquitin-conjugating enzyme E2C (UBE2C), which plays a critical role in the development of gliomas." (PMID 39594778, 2024). "Moreover, we demonstrated that the possible mechanism of the si-UBE2C-induced inhibition of glioma cell proliferation might be autophagic cell death induction and PI3K-Akt-mTOR signaling pathway inactivation." (PMID 28767320, 2017). "Therefore, exploring the potential mechanism by which FoxM1 acts on UBE2C may provide a novel therapeutic approach for treating gliomas." (PMID 28767320, 2017). "UBE2C expression was found to be positively correlated with cell cycle, proliferation, DNA damage, invasion, and MET in Glioma." (PMID 38370368, 2024). "CENPF, TOP2A, UBE2C, PBK, and MKI67 were strongly expressed in glioma clusters, indicating the presence of progenitor cells." (PMID 39333557, 2024). "To reveal the role of UBE2C in regulating TMZ resistance in gliomas, we first assessed its expression levels in the brain tissues of TMZ-resistant and TMZ-sensitive glioma patients, as well as in normal brain tissues." (PMID 38634120, 2024). "Univariate analysis and multivariate analysis of the correlation of the expression of CDC20, UBE2C, WDR62, DTL, HOXB4 and TRIM38 with OS among glioma patients." (PMID 33914773, 2021). "The genes RRM2, KIAA0101, UBE2C, LMX1A, DTL, and LBX1 demonstrated significant overexpression in all human glioma subtypes (GBM, ODG, OA, AA) with a p-value ≤ 0.0001." (PMID 31475119, 2019). "Targeting KIF11 and UBE2C using small molecule inhibitors Ispinesib and Monastrol (KIF11 inhibitors) and NSC697923 (UBE2C inhibitor) in the canine model of glioma can potentially be a promising therapeutic strategy for future evaluation in human GBM." (PMID 31475119, 2019). "Human Protein Atlas data, shows that 83% of glioma patients express moderate to high levels of KIF11 and 90% of patients express at least some level of UBE2C." (PMID 31475119, 2019). "Additionally, UBE2C had a positive relationship with both cell cycle and proliferation in in AML, CML, BRCA, GBM, Glioma, HGG, HNSCC, LUAD, MEL and RB." (PMID 38370368, 2024). "Inhibition of UBE2C in GBM has shown to result in the induction of autophagic death in glioma cells, but its inhibition has not been evaluated in GBM in clinical trials either." (PMID 31475119, 2019). "Ubiquitin-conjugating enzyme E2C (UBE2C) is characterized as a crucial molecule in cancer cell growth that plays an essential role in the development of gliomas, but the detailed mechanisms have not been fully elucidated." (PMID 28767320, 2017). "Variable UBE2C expression levels were observed at both the mRNA and protein levels in the diverse glioma cell lines, whereas there was almost no UBE2C expression in NHAs." (PMID 28767320, 2017). "However, the role of UBE2C in modulating TMZ resistance in glioma and the related mechanisms have not yet been reported." (PMID 38634120, 2024). "The immunohistochemical staining revealed that all the NHB tissues displayed no or extremely low levels of UBE2C protein expression (IRS ≦2, 27/27); however, 63% of the glioma tissues (97/154) exhibited strong UBE2C immunoreactivity (IRS ≧4)." (PMID 28767320, 2017).
non-small cell lung carcinoma (21 papers, 2016 to 2025). A group of at least three distinct histological types of lung cancer, including non-small cell squamous cell carcinoma, adenocarcinoma, and large cell carcinoma. "Forced ALKBH5 expression can stabilize ubiquitin-conjugating enzyme E2C (UBE2C) epi-transcriptionally via the maintenance of lower m6A levels within its mature RNAs in non-small cell lung cancer." (PMID 36551544, 2022). "Of note, experimental inhibition of UBE2C suppressed the malignant phenotypes, surpassing cisplatin resistance in ovarian and non-small cell lung cancers, in parallel with overcoming sorafenib resistance in HCC." (PMID 32183400, 2020). "A recent study demonstrated that UBE2C was involved in chemotherapeutic sensitivity in non-small cell lung cancer cells." (PMID 30914455, 2019). "Consistently, UBE2C has been found to be epi-transcriptionally stabilized with the maintenance of lower m6A levels within its mature RNAs in response to the increase in ALKBH5 expression in non-small cell lung cancer." (PMID 36551544, 2022). "UBE2C selectively represses autophagic death and disruption of UBE2C-mediated autophagy repression attenuates cell proliferation, clonogenicity, and invasive growth in non-small cell lung cancer (NSCLC) cells." (PMID 30914455, 2019). "In the study «The Relationship Between UBE2C and AGGF1 Overexpression and Tumor Angiogenesis in Non-Small Cell Lung Cancer» there were 154 patients." (PMID 40786517, 2025). "Particularly, in non-small cell lung carcinomas (NSCLC), UBE2C has a positive correlation with tumor grade, being overexpressed in poorly differentiated tumors." (PMID 37958776, 2023). "In non-small cell lung cancer (NSCLC), elevated UBE2C expression has been reported in cisplatin-resistant NSCLC cells, which correlates with high proliferation and invasion." (PMID 33805973, 2021). "Moreover, miR-495 could reverse cisplatin resistance in non-small cell lung cancer by regulating the expression of the drug resistance genes ABCG2 and ERCC1 and directly targeting UBE2C 3′-UTR, affecting cells growth, invasion, and metastasis." (PMID 34935899, 2022). "The positive correlation identified in this study between UBE2C expression and the presence of both LVI and nodal status implicates UBE2C in cancer invasiveness via enhancing the EMT process, which is in accordance with a previous in vivo and in vitro study of UBE2C in non-small-cell lung cancer." (PMID 35124721, 2022).
colorectal cancer (19 papers, 2014 to 2025). A primary or metastatic malignant neoplasm that affects the colon or rectum. "The dysregulation of UBE2C is associated with the upregulation of Ki-67, a proliferative marker, and poor overall survival in colorectal carcinoma." (PMID 34671679, 2021). "In colorectal carcinoma, bortezomib treatment has been demonstrated to downregulate UBE2C expression leading to decreased cell viability via stabilizing mitotic cyclins and inhibiting cell cycle progression." (PMID 37377594, 2023). "UBE2C expression was also a predictor of prognosis and sensitivity to the antineoplastic treatment for colorectal cancer patients." (PMID 31942195, 2020). "In colorectal cancer, knockdown of UBE2C sensitized the cells to pharmacological treatments with irinotecan, SN-38 and cetuximab partly through down-regulation of AKT." (PMID 30914455, 2019). "The core genes, namely MYC, MAD2L1, CENPF, UBE2C, NUF2 and NCAPG2, showed elevated expression in colorectal cancer samples, in stark contrast to their comparatively lower expression in normal samples." (PMID 38637125, 2024). "In particular, MYC, MAD2L1, CENPF, UBE2C, NUF2 and NCAPG2 were identified as highly expressed in colorectal cancer samples." (PMID 38637125, 2024). "Notably, the core genes (MYC, MAD2L1, CENPF, UBE2C, NUF2, NCAPG2) had differential expression in colorectal cancer samples in comparison to normal samples." (PMID 38637125, 2024).